LAT (linker for activation of T cells)
Diseases named in the same sentence as LAT in open-access papers (continued):
Sharing a sentence is not in itself a finding about the gene and the disease.
glioma (4 papers, 2021 to 2024). A benign or malignant brain and spinal cord tumor that arises from glial cells (astrocytes, oligodendrocytes, ependymal cells). "The advantage of metabolic imaging using 18F-FET is explained because in tissue affected by post-therapeutic changes, LAT expression is normal or even downregulated (contrary to glioma tissue, which presents an increased number of LAT)." (PMID 38201621, 2023). "Amino acid PET tracers can be useful because, as gliomas, metastatic brain tumors overexpress LAT, independently of the primitive tumor." (PMID 35205625, 2022). "Amino acid PET tracers have relatively high sensitivity for gliomas as the LAT system transporters is overexpressed in most of them, with a good tumor-to-background contrast in the brain." (PMID 35205625, 2022). "However, the tumor accumulation of FDOPA in gliomas is also mediated through the specific LAT transport system, a tight bidirectional coupling of influx and efflux with obligatory exchange." (PMID 34307430, 2021). "The estimates for the contribution of blood–brain barrier disruption and the specific LAT transport system contribution to the FDOPA uptake and washout in gliomas are not fully understood." (PMID 34307430, 2021).
prostate carcinoma (4 papers, 2019 to 2025). A carcinoma that arises from epithelial cells of the prostate gland. "LAT inhibition suppressed M-phase cell cycle genes regulated by E2F family transcription factors including critical castration-resistant prostate cancer regulatory genes." (PMID 39941741, 2025). "LAT suppression inhibited M-phase cell cycle genes regulated by E2F family transcription factors, including UBE2C, CDC20, and CDK1, which are important castration-resistant prostate cancer regulators." (PMID 35008399, 2022). "Our data confirmed that the treatment of prostate cancer cells with ENZA enhances the effect of radiation through down-regulation of NKX3-1, ZMIZ1, SPDEF and PDE9A genes and up-regulation of LAT, PTPRN2 and OSBPL10 genes in LNCaP cells, as well as up-regulation of CYP1B1 genes in C4-2 cells." (PMID 31221986, 2019).
combined immunodeficiency (3 papers, 2021 to 2024). A broad classification of inherited disorders presenting at birth that affect both the cell-mediated and humoral aspects of the immune response. "Accordingly, a recent publication reported additional patients with bi-allelic DIAPH1 mutations, and these patients displayed symptoms of combined immunodeficiency (CID) similar to those reported in LAT deficiency, in addition to microcephaly, seizures, cortical blindness, and developmental delay." (PMID 39076976, 2024).
lupus (3 papers, 2013 to 2021). "A recent study also observed an abnormal pattern of expression and localization of LAT in lipid rafts after in vitro activation of lupus T cell." (PMID 23360572, 2013). "The top pathways predicted to be deactivated were systemic lupus erythematosus in B cell signaling pathway (Z-score = −0.333), melanocyte development and pigmentation signaling (Z-score = −1), and phospholipase C signaling (Z-score = −0.447) mainly elicited by TNF family regulators, LAT, and PLCG2." (PMID 32636844, 2020).
ocular infection (3 papers, 2010 to 2025). "At a dose of 1 × 103 pfu/eye, 9 of 16 of IFNαβR−/− mice infected with LAT-plus survived ocular infection (56% survival), while only 1 of 16 IFNαβR−/− mice infected with LAT-minus virus survived ocular infection (6% survival)." (PMID 40872775, 2025). "All WT mice infected with 1 × 104 pfu/eye of either LAT-plus or LAT-minus viruses survived ocular infection (100% survival), while IFNαβR−/− mice infected with the same dose of LAT-plus or LAT-minus did not survive (0% survival)." (PMID 40872775, 2025). "IFNαβR−/− mice survived ocular infection with the LAT-plus virus, while no infected mice survived infection with the LAT-minus virus." (PMID 40872775, 2025). "In this study, we also demonstrated that, similar to LAT-plus-infected mice, in the absence of both the LAT and γ34.5 genes, all infected mice survived ocular infection." (PMID 40872775, 2025).
allergic asthma (2 papers, 2013 to 2021). A asthma with a basis in a pathological type I hypersensitivity reaction. "Our results thus indicate that LAT, regulated by histone modification, is an essential regulator in Th2 polarization in allergic asthma." (PMID 23360572, 2013). "The relative LAT mRNA level was dramatically decreased in the peripheral blood T cells from allergic asthmatic patients compared to healthy controls (P < 0.01), emphasizing the role of LAT in allergic asthma." (PMID 23360572, 2013). "Combination with our results here confirmed that LAT is involved in allergic asthma by regulating the type-2 immune responses." (PMID 23360572, 2013). "In the present study, we show that LAT mRNA was decreased in peripheral blood T cells from allergic asthmatic patients, suggesting the involvement of LAT in T cell differentiation in allergic asthma." (PMID 23360572, 2013). "LAT hypoacetylation results in the inhibition of LAT in an allergic asthma model." (PMID 34566492, 2021). "Thus, our study highlights the importance of LAT expression in allergic asthma and suggests that histone modification can influence LAT expression and regulate allergic airway inflammation." (PMID 23360572, 2013). "Our findings have important implications for therapeutically targeting LAT in allergic asthma." (PMID 23360572, 2013). "Our results indicate that histone hypoacetylation may regulate LAT expression on T cells and modify Th2 polarization in allergic asthma." (PMID 23360572, 2013). "Linker for activation of T cells (LAT), a transmembrane adaptor protein, plays a role in T cell and mast cell function, while it remains unclear how histone modifications mediate LAT expression in allergic asthma." (PMID 23360572, 2013). "However, the function of histone modification in LAT expression in allergic asthma has not been addressed." (PMID 23360572, 2013). "However, whether LAT is involved in the pathogenesis of allergic asthma has not been clearly identified." (PMID 23360572, 2013).
brain tumor (2 papers, 2022 to 2023). "Their uptake is facilitated by large neutral amino acid transporters of the L‐type (LAT) in gliomas and brain metastases (i.e., subtypes LAT1 and LAT2), which are regularly overexpressed in both brain tumor types." (PMID 36577872, 2023). "High LAT-1HD expression at the BBB and in brain tumors can be used for the PET imaging of tumors with radiolabeled amino acid tracers and as a potential target for cancer pharmacotherapy." (PMID 35408997, 2022). "Because it is highly expressed in brain tumors and due to its importance at the BBB, LAT-1HD is of particular interest for currently difficult-to-treat brain tumors." (PMID 35408997, 2022). "A potential dual targeting of brain tumors, based on the high expression of LAT-1HD in both the BBB and brain tumors, could contribute to the development of effective treatment options." (PMID 35408997, 2022).
eosinophilia (2 papers, 2018 to 2025). "Notably, CNV analysis in two NDD children revealed mutated regions encompassing the ADA gene, associated with both ASD and eosinophilia, and the LAT gene, crucial for brain development and amino acid transport regulation." (PMID 41346380, 2025).
T cell lymphoma (2 papers, 2015 to 2023). "GRB2 knockdown and re-expression of selected monomeric and dimeric mutants in a T cell lymphoma cell line led to notable defects in clustering of the adaptor protein LAT and IL-2 release in response to TCR stimulation." (PMID 36864087, 2023).
type 1 diabetes (2 papers, 2019 to 2025). "LAT as a gene involved in KEGG immune and inflammatory pathways, whereas PTPRN2 and PDE9A were previously shown to be associated with type I diabetes mellitus pathway and purine metabolism, respectively." (PMID 31221986, 2019).
adrenal autoimmunity (1 paper, 2025). "Beyond common variants, rare variants in immune genes such as RAG1, TNFAIP3 (A20), LAT, and IKZF2 (HELIOS) have been described in autoimmune syndromes that include adrenal autoimmunity." (PMID 41465179, 2025).
Arthritis (1 paper, 2024). Inflammation of a joint. "We found that the redox insensitivity of LAT affects its localization and phosphorylation, leading to changes in T cell selection, susceptibility to inflammation, and development of arthritis, an effect reversed by the NCF1 mutation." (PMID 38671946, 2024). "Antibodies against F4 have been shown to ameliorate arthritis severity and could be a regulatory feedback mechanism to the loss of control induced by the oxidation-insensitive mutant LAT." (PMID 38671946, 2024). "An interplay between ROS and LAT from studies of arthritis has been suggested; synovial fluid (SF) T cells from RA patients have been hypothesized to be hypoactive due to the redox-dependent displacement of LAT from the membrane to the cytoplasm, an effect possibly mediated by its cysteine residues." (PMID 38671946, 2024).
asthma (1 paper, 2013). "Our results demonstrated that the expression of LAT mRNA in peripheral blood T cells from patients with asthma decreased, as compared to healthy controls." (PMID 23360572, 2013). "In an allergen-induced asthma model, histone hypoacetylation on LAT promoter inhibited LAT expression and enhanced Th2 differentiation." (PMID 23360572, 2013). "The present study aimed at understanding alterations of lymphocyte LAT in patients with asthma and potential mechanisms by which histone modulation may be involved in." (PMID 23360572, 2013).
bacterial sepsis (1 paper, 2017). "Some of the hemostasis genes that we identified as candidaemia susceptibility genes (SERPINA1, LAT and F5) have also been shown to be important for bacterial sepsis." (PMID 28727728, 2017).
breast tumor (1 paper, 2013). "GRB2 interaction with LAT and LAX1 observed in breast tumor cells may be an indirect interaction through PLCG1, VAV or PIK3R1." (PMID 23826330, 2013).
celiac disease (1 paper, 2025). An autoimmune genetic disorder with an unknown pattern of inheritance that primarily affects the digestive tract. "The autoimmune upregulation of LAT in celiac disease may be driven by chronic signaling through stress receptors such as NKG2D and CD94, as well as IL-15 that is highly expressed in active disease." (PMID 40463269, 2025). "Interestingly, in active celiac disease, LAT is highly upregulated in natural T-IEL, suggesting LAT may be potentiating autoimmune responses in this context." (PMID 40463269, 2025).
cholangiocarcinoma (1 paper, 2013). A carcinoma that arises from the intrahepatic biliary tree (intrahepatic cholangiocarcinoma) or from the junction, or adjacent to the junction, of the right and left hepatic ducts (hilar cholangiocarcinoma). "We found that BCH as a competitive LAT inhibitor suppressed proliferation of cholangiocarcinoma cells and yielded an additive therapeutic efficacy to GEM and 5-FU in vitro." (PMID 24131658, 2013). "The inhibition of LAT significantly suppressed the growth of cholangiocarcinoma, and anti-tumor efficacy of GEM and 5-FU was augmented in combination with LAT inhibitor." (PMID 24131658, 2013).
chronic hepatitis (1 paper, 2018). An active inflammatory process affecting the liver for more than six months. "MAP2K7 and MAPK14 were highly expressed in chronic hepatitis; LAT, SOS2, and BCL‐10 were highly expressed in normal tissues; PTPN6, LCK, and CTLA4 were highly expressed in CS." (PMID 30259695, 2018).
depression (1 paper, 2023). "In summary, our study showed that LAT has a comparable anti-depression effect as fluoxetine in a model of CSDS-induced depression." (PMID 37400661, 2023). "Further studies will be required to determine whether LAT has the same therapeutic effect on other models of depression." (PMID 37400661, 2023). "The current observation in our study that LAT reduces CSDS-induced increase in IL-6 and TNF-α, concomitant with the mitigation of depression-like behavior, strongly supports this hypothesis." (PMID 37400661, 2023).
glaucoma (1 paper, 2020). Increased pressure in the eyeball due to obstruction of the outflow of aqueous humor. "In addition, TPI displayed additive effects to LAT, suggesting their possible use in combination therapy in the treatment of glaucoma and OH." (PMID 32994409, 2020).
head and neck cancer (1 paper, 2021). A primary or metastatic malignant neoplasm affecting the head and neck. "A recent study suggested that overexpression of LAT in head and neck cancer was associated with a good prognosis based on an in silico investigation using gene expression data from the TCGA." (PMID 34885177, 2021).
inflammatory bowel disease (1 paper, 2024). A spectrum of small and large bowel inflammatory diseases of unknown etiology. "In 5-Tm, GOs including Th17 differentiation pathway, inflammatory bowel disease, and allograft rejection, represented by IL12RB1, IRF4, LAT, and IL22, were observed in PE." (PMID 38774869, 2024).
leukemia (1 paper, 2015). A malignant (clonal) hematologic disorder, involving hematopoietic stem cells and characterized by the presence of primitive or atypical myeloid or lymphoid cells in the bone marrow and the blood. "miR-155 is a microRNA that is correlated with hyperproliferation in a number of cancers including lymphomas and leukemias and is overexpressed in mutant LAT T cells." (PMID 26121028, 2015).
lymphoma (1 paper, 2015). A malignant (clonal) proliferation of B- lymphocytes or T- lymphocytes which involves the lymph nodes, bone marrow and/or extranodal sites. "We found that miR-155 is elevated in LAT-KI T cells as well as it is in many cancers and especially lymphomas." (PMID 26121028, 2015).
ovarian carcinoma (1 paper, 2021). A malignant neoplasm originating from the surface ovarian epithelium. "Due to the transcription-promoting and LAT activity, CBP is involved in multiple cellular functions and pathological processes especially in tumorigenesis 26-30, but its effect on ovarian cancer has not been fully explored." (PMID 34149923, 2021).
pericarditis (1 paper, 2026). An inflammatory process affecting the pericardium. "Among them, elevated levels of NEU1, GDNF, and LAT increased the risk of pericarditis, whereas higher levels of CASP8, ZFYVE27, and NAPA decreased the risk of pericarditis." (PMID 41674924, 2026).
rheumatoid arthritis (1 paper, 2024). A chronic, systemic autoimmune disorder characterized by inflammation in the synovial membranes and articular surfaces. "Importantly, redox insensitivity of LAT enhanced T cell-dependent autoimmune inflammation in collagen-induced arthritis (CIA), a mouse model of rheumatoid arthritis (RA)." (PMID 38671946, 2024).
sialadenitis (1 paper, 2021). Sialadenitis is an infection of the salivary glands. "The development of sialadenitis was found to be inhibited in the anti-CCL8 Ab-treated LAT mice when compared with the control Ig-treated mice." (PMID 34391459, 2021). "We confirmed that LAT mice had a type 2 cytokine-dominant immune environment that reported in IgG4-RD including IgG4-ralated sialadenitis, while Treg cells were decreased in LAT mice." (PMID 34391459, 2021). "In conclusion, we have demonstrated that upregulation of the mCCL8 (analog of hCCL18)–CCR8 axis in LAT mice could play a crucial role in fibrosis via ERK1/2 pathway-dependent type-I collagen production, as well as in cell infiltration in sialadenitis." (PMID 34391459, 2021).
Splenomegaly (1 paper, 2021). Abnormal increased size of the spleen. "The absence of B cells in RAG-/- hosts prevented splenomegaly and T cell expansion, which was only seen in LAT-/- host upon transfer of ERCre+LATf/m CD4+ T cells." (PMID 33912184, 2021).
thyroid cancer (1 paper, 2025). "Sodium butyrate could upregulate the expression of LAT protein, a transporter for BPA, leading to increased absorption of BPA in thyroid cancer cells." (PMID 41179690, 2025).
trigeminal neuralgia (1 paper, 2024). Trigeminal neuralgia is a nerve disorder that causes a stabbing or electric-shock-like pain in parts of the face. "Unlike LAT, which is more prevalent in nerve ganglia in trigeminal neuralgia, miR-H6 maintains latency and activates productive disease activation." (PMID 39480863, 2024).
ulcerative colitis (1 paper, 2025). An inflammatory bowel disease involving the mucosal surface of the large intestine and rectum. "In conclusion, this study provides the first evidence that ceAF can mitigate ulcerative colitis (UC) and TNF-α-induced inflammatory responses by inhibiting the LCK/ZAP70/LAT signaling pathway, thereby reducing TCR signaling hyperactivation." (PMID 39857385, 2025).